CDK4 (cyclin dependent kinase 4)
Diseases named in the same sentence as CDK4 in open-access papers (continued):
Sharing a sentence is not in itself a finding about the gene and the disease.
breast cancer (continued). "This study investigates the outcomes associated with two kinds of CDK4/6i in patients with hormone receptor (HR)-positive metastatic and relapsed breast cancer to inform real-world evidence of treatment strategies." (PMID 39133334, 2024). "E2F8 has been associated with CDK4/6 inhibitor resistance, is overexpressed in patients with breast cancer, and has been significantly correlated with poor patient survival and cancer progression." (PMID 39057065, 2024). "In breast cancer, overactivation of CDK4 causes abnormal cell cycles that promote the proliferation and metastasis of tumor cells." (PMID 38215156, 2024). "This implies a potential effect of HER2-low status on the response to CDK4/6 inhibitors in HR+/HER2- breast cancer, possibly associated with resistance mechanisms." (PMID 39730704, 2024). "Abemaciclib, a CDK4/6 inhibitor approved for the treatment of metastatic luminal breast cancer is very frequently associated with elevations in sCr, although this does not seem to represent true kidney injury." (PMID 39318897, 2024). "The combination of CDK4/6 inhibitors with mTORC1/2 inhibitors has been demonstrated to cause breast cancer cell apoptosis and inhibit Rb (retinoblastoma) phosphorylation and E2F-mediated transcription in CDK4/6 resistant cells." (PMID 38396649, 2024). "CDK4 is an enzyme that works with cyclin D1 to promote cell cycle progression by activating Rb, and overexpression of CDK4 has been linked to certain types of breast cancer, as well as other cancers." (PMID 38332687, 2024). "The overexpression of the tumor suppressor protein p16 has been associated with estrogen receptor-positive breast cancer cell lines and a diminished response to CDK4/6 inhibitors in breast cancer patients." (PMID 39702350, 2024). "In CDK4/6 inhibitor-resistant ER+/RB-deficient breast cancer, PRMT5 inhibition represents a viable therapeutic strategy, leading to the dissociation of FUS from RNA polymerase II and subsequently suppressing the DNA synthesis." (PMID 39678513, 2024). "More recently, the CDK4/6i abemaciclib was also approved for high-risk patients with early-stage ER+ breast cancer in combination with tamoxifen or an AI." (PMID 39931212, 2024). "PR-negative and first-line POD24 occurrence were risk factors of advanced ER-high HER2-negative breast cancer patients receiving CDK4/6 inhibitor combined with endocrine as first-line therapy." (PMID 39020297, 2024). "Alpelisib plus fulvestrant displayed an overall response rate (ORR) of 19.0% and median progression-free survival (PFS) around 11 months in PIK3CA-mutated HR+ advanced breast cancer patients progressing on or after treatment with CDK4/6i and/or ET." (PMID 39409880, 2024). "In the clinic, high PLK1 levels have been associated with resistance to cyclin-dependent kinase 4/6-targeted therapy in luminal breast cancer, and to estrogen-targeted therapy." (PMID 39513002, 2024). "CDK4 and cyclin D1 overexpression has been reported to cause resistance to CDK4/6 inhibitors in breast cancer cells." (PMID 39123441, 2024). "Here, the authors identify microphthalmia-associated transcription factor-A (MITF-A) as a driver of CDK4/6 inhibitor resistance in breast cancer and show that MITF-A activity is mediated through O-GlcNAcylation at Serine 49, promoting its nuclear import." (PMID 38961064, 2024). "In conclusion, the CDK4/6-USP51-ZEB1 axis is a key regulatory pathway in breast cancer metastasis that can be exploited for diagnostic and therapeutic purposes in the future." (PMID 39196911, 2024). "Collectively, these data support PRMT5 as a therapeutically actionable vulnerability to overcome resistance to CDK4/6 inhibitors in ER+/RB-deficient breast cancer." (PMID 38480701, 2024). "This study shows that RET overexpression is associated with resistance to combined CDK4/6i and fulvestrant treatment in ER+ breast cancer cell lines." (PMID 39931212, 2024).
breast cancer (continued). "Of note, suppression of the TGFβ signalling pathway has previously been associated with resistance to CDK4/6 inhibitors through an extracellular miRNA-mediated mechanism in ER + breast cancer." (PMID 38831405, 2024). "In Costa's research, loss of PTEN was found in patients with breast cancer resistance to CDK4/6 inhibitors." (PMID 36825764, 2023). "The development of endocrine resistance in breast cancer is usually associated with the deregulation of the cyclin-dependent kinase 4 (CDK4) and CDK6/retinoblastoma pathway." (PMID 37519806, 2023). "The spectrum of CDK4/6i Induced cAEs shares some similarities with the dermatological toxicities caused by ET for adjuvant breast cancer treatment." (PMID 37509319, 2023). "With the increased use of CDK4/6i as the standard-of-care for ER+ breast cancer, it is anticipated that RB-deficient breast cancer will become a rising patient population in need of novel therapeutic strategies." (PMID 37502925, 2023). "Deregulation of the CDK4/6-Cylin D-Rb pathway occurs in 90% of breast cancers and is known to be a hallmark of cancer." (PMID 36985460, 2023). "Another study uncovered RB and PTEN loss as a key factor in acquired CDK4/6i resistance in ER-positive advanced breast cancer." (PMID 38037159, 2023). "Dysregulation of cyclin-dependent kinases (CDKs), mainly CDK4/6 and retinoblastoma protein (RB) pathway induces sustained cellular proliferation and has been associated with the pathogenesis of HR+ breast cancer." (PMID 38017459, 2023). "In ER + breast cancer, overexpression of p16 has been associated with CDK4/6 inhibitor resistance and poor clinical outcome." (PMID 37035239, 2023). "Some studies have indicated that the overexpression of cyclin D1 or CDK4 caused tumor in mice, while knockout cyclin D1 or CDK4 caused resistance to the development of murine breast cancer." (PMID 36838737, 2023). "ER loss occurs in a minority of ER + breast cancer through the course of therapy, is associated with ET resistance, and remains an important predictor of CDK4/6 inhibitor and ET efficacy." (PMID 37035239, 2023). "The secondary endpoints were to decipher the mutation types across breast cancer subtype, menopausal status, and time to treatment failure after everolimus (an mTOR inhibitor) or cyclin-dependent kinase 4/6 (CDK4/6) inhibitor treatment." (PMID 37655108, 2023). "Therapeutic options for early-stage ER/PR+ breast cancer include adjuvant endocrine therapy, and for clinical or genomic high-risk ER/PR+, neoadjuvant or adjuvant chemotherapy, as well as adjuvant cyclin-dependent kinase 4/6 inhibitors (CDK4/6i)." (PMID 38132377, 2023). "Breast cancer is associated with the imbalance of D-cyclin dependent kinase 4/6-retinoblastoma (cyclin D-CDK4/6-retinoblastoma) pathway." (PMID 37063263, 2023). "Recently, both the American Food and Drug Administration (FDA) and Health Canada have approved the use of abemaciclib (CDK4/6 inhibitor) for patients with HR+/HER2: high-risk early breast cancers in the adjuvant setting." (PMID 36975446, 2023). "Our findings confirm that treatment with CDK4/6 inhibitors for advanced breast cancer impairs the immune response to tozinameran and is a risk factor for the development of breakthrough infections despite the third vaccine dose." (PMID 38023235, 2023). "In this study, we demonstrated that the high PEG10 expression is one of the mechanisms associated with acquired CDK4/6 inhibitor resistance in HR+ breast cancer." (PMID 38017459, 2023). "Together, these data suggest that there are distinct pathological and biological features of HR+/HER2− breast cancer associated with response to CDK4/6 inhibitors." (PMID 37704753, 2023).
breast cancer (continued). "Studies have shown a controversial association between PgR levels and benefit from CDK4/6i in breast cancer." (PMID 36717797, 2023). "Taken together, these data support PRMT5 as a therapeutically actionable vulnerability to overcome resistance to CDK4/6 inhibitors in ER+/RB-deficient breast cancer." (PMID 37502925, 2023). "While CDK2 hyperactivation is linked to basal-like breast cancer tumors, aberrant expression of CDK4 is linked to drug resistance." (PMID 37596623, 2023). "In conclusion, our research demonstrated that WXJ-202 induced apoptosis and cycle arrest through affected CDK4/6-Rb-E2F pathway-associated proteins, producing antitumor effects on breast cancer cells in vitro and in vivo." (PMID 36744210, 2022). "The PI3K-PDK1 signaling pathway has been implicated in mediating resistance to CDK4/6 inhibitors, with ribociclib-resistant breast cancer cell lines demonstrating an increase in PDK1 levels following drug exposure, resulting in activation of the AKT pathway." (PMID 35053461, 2022). "For breast cancer, various preclinical studies suggested loss of Rb to be a driver of resistance to CDK4/6 inhibitors." (PMID 35053461, 2022). "In a recent study, intrinsic resistance to Palbociclib was linked to a lysosomal gene signature in luminal ER+ breast cancer, suggesting that in some ER+ breast cancer cells, the lysosome sequesters CDK4/6 inhibitors, as demonstrated for TNBC cells." (PMID 36077830, 2022). "Our results demonstrated that PI3K inhibitors showed prominently therapeutic efficacy in PIK3CA-altered HPVneg HNSCC while CDK4/6 inhibition has also been proven to improve the response to PI3K inhibitors in PIK3CA-mutated breast cancers." (PMID 35546399, 2022). "Another in vitro study in breast cancer cells has reported loss of the FAT1 as a mechanism for induction of resistance to CDK4/6 inhibitors." (PMID 36266723, 2022). "CDK4/6 overexpression results in abnormalities in the CDK4/6-Rb-E2F pathway, which is a core cause of the development of breast cancer." (PMID 36744210, 2022). "Overexpression of CDK4/6 leads to abnormalities in the CDK4/6-Rb-E2F pathway, which is an essential cause of the development of breast cancer." (PMID 36744210, 2022). "For instance, one recent study showed that treatment with CDK4/6 inhibitors in ER+ breast cancer causes extensive enhancer activation through activator protein-1 (AP-1) transcriptional changes." (PMID 36176758, 2022). "According to SOLAR-1 (NCT02437318) and BYLieve (NCT03056755, cohort A) trials, breast cancer patients carrying PIK3CA mutations who received any CDK4/6 inhibitor and fulvestrant treatment followed by alpelisib had a better prognosis." (PMID 36058938, 2022). "There is growing evidence that patients with gBRCA ER+/HER2- advanced breast cancer are at higher risk of early disease progression under CDK4/6 inhibitors than their counterparts with wild-type BRCA disease." (PMID 35805038, 2022). "We previously showed that in extracranial models of HER2 + breast cancer, resistance to HER2-targeted therapy in HER2 + breast cancer is mediated by upregulation of cyclin D1 and CDK4, thus, susceptible to CDK4/6 inhibition." (PMID 35304445, 2022). "Results from the more recent phase 2 BYLieve study indicate that alpelisib in combination with endocrine therapy (fulvestrant or letrozole) is also effective in patients with HR+, HER2–, PIK3CA-mutated breast cancer in the post-CDK4/6 inhibitor setting." (PMID 35406370, 2022). "Miller and colleagues have shown that chronic deprivation of estrogen can lead to the hyper-activation of the PI3K/AKT signaling pathway and sustained CDK4-E2F activation, thus causing estrogen resistance in breast cancer cells." (PMID 33809714, 2021). "This post-marketing research addressed the role of cyclin-dependent kinase 4/6 inhibitors, relatively new anticancer drugs approved for advanced breast cancer in cancer-associated thrombosis." (PMID 33917020, 2021).
breast cancer (continued). "Since the loss of p16 (CDKN2A) expression has been associated with sensitivity to the CDK4/6 inhibitor palbociclib in melanoma cell lines and breast cancer patient, we further investigated p16 RNA and protein expression in metastatic lung lesion and PDX-mlung." (PMID 34885073, 2021). "The presence of BCSCs is also an important cause of ET resistance in luminal breast cancer, which can be regulated by the cyclin-dependent kinase 4/6 (CDK4/6) complex and mechanistic target of rapamycin (mTOR) signaling." (PMID 33672204, 2021). "In keeping with these results, RB1-deficient breast cancer cell lines exhibited strongly diminished response to CDK4/6i treatment." (PMID 34508104, 2021). "Many cancers, including breast cancer, acute myeloid leukaemia, non–small‐cell lung cancer and ovarian cancer, have been found to be associated with the dysregulation of CDK4." (PMID 33452764, 2021). "To date, no successful therapies have been found to target KRAS mutations in ER+ CDK4/6 inhibitor-resistant breast cancer." (PMID 34830174, 2021). "Aberrant activation of the cyclin D1-CDK4/6-retinoblastoma (Rb) pathway is hallmark of breast cancer that led to the development of CDK4/6 inhibitors." (PMID 33599863, 2021). "Copy number alteration of CDK2 is associated with dysfunctional T-cell phenotype, high death risk, and shorter survival of lymphoma, leukemia, and breast cancer patients while CDK4 predicted a worse prognosis of the brain, lymphoma, and breast cancer patients." (PMID 33668805, 2021). "Recently, a preclinical study reported a lethal interaction between an aurora A inhibitor and loss-of-function mutations in Rb in a panel of cancer cells, including CDK4/6i-resistant breast cancer cell models." (PMID 34771560, 2021). "As expected, the higher expression profiles of CDK2 and CDK4 were associated with high risk scores and shorter survival periods of the breast cancer cohorts." (PMID 34421361, 2021). "In agreement with this, combinatorial use of the CDK4/6 inhibitor LEE011 plus BYL719 or GDC-0941 caused tumor regression in breast cancer xenograft models." (PMID 33809714, 2021). "This landmark study raises the possibility of utilizing CDK4/6 inhibitors for high-risk patients to improve outcomes in early breast cancer." (PMID 34609096, 2021). "Because estrogen is mitogenic, and thus leads to increases in both cyclin D1 and CDK4/6 activity, it causes excess proliferation in hormone-regulated breast cancers." (PMID 34830174, 2021). "Due to mutations like these, targeting CDK4/6 in ER+ breast cancer effectively elicits a response in endocrine-resistant patients." (PMID 34830174, 2021). "Alterations in the cyclin-D-CDK4/6-retinoblastoma pathway were associated with endocrine resistance in breast cancer, and the CDK4/6 inhibitors had shown its ability to reverse endocrine resistance." (PMID 33193875, 2020). "Levels of CDK4 and Cyclin D1, both of which are important molecular markers associated with cell-cycle progression, decreased following AG-205 treatment in both breast cancer cell lines." (PMID 32704174, 2020). "Our study also demonstrated that the combination of CDK4/6i and PARPi showed synergy in not only RB-proficient but also in RB-deficient breast cancer cells." (PMID 32249776, 2020). "All the six cases of MRONJ associated with CDK4/6 inhibitors assumed concomitantly with intravenous bisphosphonates and/or denosumab had breast cancer." (PMID 33353034, 2020). "We observed six cases of MRONJ associated with CDK4/6 inhibitors concomitantly with intravenous bisphosphonates and/or denosumab in breast cancer patients." (PMID 33353034, 2020). "TROJAN promoted cell proliferation and resistance to a CDK4/6 inhibitor and was associated with poor survival in ER+ breast cancer." (PMID 32393270, 2020). "The identification of several mutational cancer drivers, including ER, HER-2, PIK3CA, and CDK4/6, promoted the development of stratified medicine in breast cancer." (PMID 32902412, 2020).
breast cancer (continued). "The combination of CDK4/6i and PARPi showed synergy in not only RB-proficient but also in RB-deficient breast cancer cells in a reactive oxygen species (ROS)-dependent manner." (PMID 32249776, 2020). "The presence of the BCSCs is also regarded as the main cause of resistance to hormonal therapy in luminal breast cancer, which can be regulated by the CyclinD-CDK4/6 (cyclin-dependent kinase 4/6) complex and mTOR signaling." (PMID 31555586, 2019). "Reduced p16 expression and increased CDK4/6 expression are often observed in cancer cells and cancer-associated fibroblasts (CAFs) in breast cancer and head and neck cancer and can induce hyperproliferation and cancer cell spread." (PMID 30828336, 2019). "Breast cancer cell lines characterized by loss of RB1 activity are hyposensitive to CDK4/6 inhibitors; however, loss of RB1 function is rare in ER-positive breast cancer." (PMID 31448056, 2019). "The cyclin D–CDK4/6–inhibitor of CDK4 (INK4)–retinoblastoma (Rb) pathway is frequently disrupted in HR+ breast cancer, and has been associated with a poor clinical outcome and resistance to endocrine therapy." (PMID 29164421, 2018). "The correlations between mutational status and response to CDK4/6 inhibition are also clear in breast cancer, where downregulation of CDKN2A and amplification of CDK4 or CDK6 were correlated with sensitivity to CDK4/6 inhibition." (PMID 29644000, 2018). "The successful implementation of combined CDK4/6 inhibitors and hormonal/endocrine therapy in clinical practice for breast cancer lays the groundwork for other CDK and CDK-associated inhibitors currently under development." (PMID 30135856, 2018). "We have also reported that inhibition of MGMT in an in vitro breast cancer model is associated with CDK4 inhibition and enhances palbociclib and abemaciclib effect." (PMID 30038716, 2018). "One study demonstrated that expression of p16INK4a, an inhibitor of cyclin-dependent kinase 4 associated with cellular senescence, increased after adjuvant chemotherapy in 33 patients with breast cancer, and remained elevated 12 months after treatment." (PMID 28851415, 2017). "Taken together, these data show that MALAT1 is positively associated with CDK4 and negatively associated with miR-124 in clinical breast cancer tissues, which increased CDK4 expression though miR-124 in breast cancer cells." (PMID 26918449, 2016). "CDK4/6 inhibition yields the repression of genes that are associated with risk of recurrence in ER+/HER2- breast cancer and functionally converts a luminal B like pattern of gene expression towards a luminal A form of disease." (PMID 27564114, 2016). "Downregulation of MALAT1 (long noncoding RNA metastasis-associated lung adenocarcinoma transcript 1) inhibits breast cancer cell proliferation and cell cycle progression in vitro and in vivo through miR-124 downregulation and CDK4 upregulation." (PMID 27818681, 2016). "We previously demonstrated that Antp-TPR peptide induced cancer-cell death through the loss of client proteins of Hsp90 such as CDK4 and Akt in breast cancer T47D cells." (PMID 22913813, 2012). "Both CDKIs are required for cyclin D assembly with CDK4 and its stability and nuclear localization, and p27 levels were significantly associated with cyclin D1 and E expression in some breast cancer cell lines." (PMID 20300579, 2009). "Of interest, Wang and colleagues recently described a cyclin D1 splice variant - named cyclin D1b - that occurs in breast cancer tissue and cell lines, and whose expression can overcome cell cycle arrest induced by anti-estrogens via a CDK4 interaction." (PMID 19874578, 2009). "However, we show here that while CDK4/6i-treated breast cancer cells exhibit various senescence-associated phenotypes, they remain insensitive to common senolytic compounds." (PMID 39930269, 2025).